LOXL1 (lysyl oxidase like 1)
Diseases named in the same sentence as LOXL1 in open-access papers (continued):
Sharing a sentence is not in itself a finding about the gene and the disease.
rheumatoid arthritis (1 paper, 2024). A chronic, systemic autoimmune disorder characterized by inflammation in the synovial membranes and articular surfaces. "Area under the ROC curve (AUC) value greater than 0.8 was considered as a condition for good diagnostic value, and DDR2 and LOXL1 performed well in distinguishing normal and rheumatoid arthritis samples." (PMID 38217541, 2024). "Here, our team reported for the first time that the basement membrane-associated gene LOXL1 was significantly upregulated in RA samples compared with healthy samples, suggesting that LOXL1 may be involved in disease progression in rheumatoid arthritis." (PMID 38217541, 2024). "Therefore, we investigated the ratio of LOXL1 and DDR2 to different immune cell infiltrations between rheumatoid arthritis and normal samples, aiming to determine the association between the infiltration status of immune cells and the expression levels of LOXL1 and DDR2." (PMID 38217541, 2024). "To further validate the role of LOXL1 in rheumatoid arthritis, we simulated the inflammatory environment of rheumatoid arthritis in vitro by stimulating SW982 cells with TNF-α." (PMID 38217541, 2024). "Real-time PCR, western blot and immunohistochemistry demonstrated that LOXL1 expression was significantly upregulated in synovial tissues of common osteoarthritic diseases, especially in rheumatoid arthritis." (PMID 38217541, 2024). "Later we will focus on exploring the role of LOXL1 in the development of rheumatoid arthritis." (PMID 38217541, 2024). "Our findings suggested that DDR2 and LOXL1 may be involved in the progression of rheumatoid arthritis by influencing the activities of multiple immune cells." (PMID 38217541, 2024). "In summary, basement membrane-localized LOXL1 may mediate the inflammatory response of rheumatoid arthritis synovial cells by influencing the activation of the PI3K/AKT pathway, thereby promoting their disease progression." (PMID 38217541, 2024). "Focusing on the more interesting LOXL1, we found that LOXL1 expression was significantly elevated in the synovium of patients with rheumatoid arthritis, and LOXL1 mRNA and protein levels were elevated in tumor necrosis factor α-stimulated human synovial sarcoma cells (SW982)." (PMID 38217541, 2024). "Finally, we proposed and validated that the differentially expressed gene LOXL1 may influence the disease process by affecting the PI3K/AKT signaling pathway mediating inflammation in rheumatoid arthritis synovial cells." (PMID 38217541, 2024). "However, the expression and role of LOXL1 in rheumatoid arthritis remain unclear." (PMID 38217541, 2024). "We concluded from the study of basement membrane-associated gene LOXL1 that LOXL1 may decelerate RA synovial inflammation by inhibiting the activation of PI3K/AKT signaling pathway, and LOXL1 may be a potential diagnostic biomarker and therapeutic target for rheumatoid arthritis." (PMID 38217541, 2024). "Finally, we have not been able to clarify how LOXL1 plays a role in the development of rheumatoid arthritis in vivo." (PMID 38217541, 2024).
sarcoidosis (1 paper, 2022). Sarcoidosis is a multisystemic disorder of unknown cause characterized by the formation of immune granulomas in involved organs. "In our study, LOXL1 and LOXL4 showed increased expression in the IPF group, as well as LOXL2 and LOXL4 in the sarcoidosis group." (PMID 35203313, 2022).
serous ovarian carcinoma (1 paper, 2020). "The results indicated that the overexpression of LOX, LOXL1, LOXL2, LOXL3, and LOXL4 mRNA in serous ovarian carcinoma patients was related to unfavorable OS and PFS." (PMID 33058284, 2020).
skin tumors (1 paper, 2022). "Similar to our observations in Itga11−/− skin tumors, LOXL1 expression was decreased in Itga11−/− mouse embryonic fibroblasts." (PMID 36003785, 2022).
uterine carcinosarcoma (1 paper, 2025). A usually aggressive malignant neoplasm arising from the uterine corpus and less often the cervix. "Among these, the mutation frequency of LOXL1 is highest in uterine corpus endometrial carcinoma, while the amplification frequency is highest in uterine carcinosarcoma." (PMID 40786111, 2025).
tumor (53 papers, 2010 to 2025). "Analysis of TCGA tumor samples shows that the most common point mutations in LOXL1 are D525N and R562H/C." (PMID 40786111, 2025). "Our analysis revealed that TPM4 and LOXL1 exhibited strong associations with lymph node metastasis and tumor size in PTC." (PMID 40740237, 2025). "Second, it is also pivotal to explore the underlying molecular mechanisms by which LOXL1 modulates tumor immune microenvironment and consequently affects immunotherapy efficacies." (PMID 38267662, 2024). "IHC assessments on a tissue microarray containing 208 pairs of CRC tissues corroborated the augmented LOXL1 protein expression in tumor tissues, with a significant association to poorer differentiation status." (PMID 38267662, 2024). "We observed distinct tumor-associated immune cells compositions in CRC samples with varying LOXL1 expression levels." (PMID 38267662, 2024). "Genetic alterations and transcriptional changes in Loxl1 were significantly associated with the tumor immune microenvironment." (PMID 38978755, 2024). "Our results also revealed a close relationship between Loxl1 mutation and tumour susceptibility, with a higher mutation frequency and lower overall survival rate observed in patients with Loxl1 mutations." (PMID 34105806, 2021). "Lastly, we demonstrated the correlation among Loxl1 deficiency, tumorigenesis and poor survival rate in patients with tumours." (PMID 34105806, 2021). "Patients with tumours had higher Loxl1 mutation frequencies, and patients with Loxl1‐mutant tumours showed the upregulation of immune processes and cell proliferation and lower survival rates." (PMID 34105806, 2021). "Similarly, LOXL1 has been associated with tumor invasion, metastasis, and extracellular accumulation of lactate, linked to integrin α11, a stromal collagen receptor." (PMID 36076905, 2022). "As LOXL1 deficiency can induce changes in the immune system and tissue hyperproliferation, which are the hallmarks of tumours, we hypothesized that mutations in LOXL1 are correlated with cancer progression." (PMID 34105806, 2021). "We previously reported that Loxl1 expression was down-regulated in integrin α11-deficient mouse tumor stroma, suggesting that integrin α11 may regulate LOXL1 expression." (PMID 31121900, 2019). "Additionally, with a goal of predicting the survival probability for CRC patients in clinic, a risk estimation nomogram based on the two independent risk factors (tumor stage and LOXL1) was established and scores were calculated to predict 1-, 3- and 5-year OS for individual patient." (PMID 38267662, 2024). "LOXL1 high expression group was characterized by escalated infiltration of immunosuppressive components, while LOXL1 low expression group was linked to a richer infiltration of anti-tumor immune cell signatures, including CD8 + T cells and interferon-γ signatures." (PMID 38267662, 2024). "Results showed that HSF4 knockout reduced tumour size, and unexpectedly, the combination of HSF4 knockout and LOXL1 overexpression further reduced tumour proliferation." (PMID 39881364, 2025). "The results showed that HSF4 knockout significantly reduced the number of liver metastases and, combined with LOXL1 overexpression, further decreased the number of metastatic tumours in the liver." (PMID 39881364, 2025). "The article focuses on examining the structure and function of LOXL1, its connection to cancer, and its involvement in tumor microenvironment remodeling, tumorigenesis, metastasis, along with the underlying molecular mechanisms." (PMID 40786111, 2025). "Recent research has revealed that LOXL1 is often overexpressed in a majority of cancers, where it plays a role in regulating tumor growth and metastasis." (PMID 40786111, 2025). "The increased expression of LOXL1 and LOXL2, along with tumor type, are independent factors associated with a poor prognosis for PM patients." (PMID 40786111, 2025).
tumor (continued). "Using differential gene expression analysis between classical Fb subtypes and CAFs, we identified CAF-enriched transcripts, including Postn, Cilp, Loxl1, Thy1, and Pi16, previously associated with CAF identity in various tumor types." (PMID 41223283, 2025). "We comprehensively unveiled the correlation between LOXL1 expression and prognosis, clinicopathological features, tumor molecular characteristics, and tumor immune microenvironment in CRC patients." (PMID 38267662, 2024). "Third, using single-cell analyses, we found that Loxl1 contributed to tumor invasion in GBM and conducted experiments in vitro." (PMID 38978755, 2024). "The detailed regulatory mechanism and interactions with Loxl1 in GBM tumor microenvironments should be addressed in future studies." (PMID 38978755, 2024). "Comprehensive annotation of biological processes and signaling pathways suggested the role for LOXL1 in modulating the tumor immune microenvironment in CRC." (PMID 38267662, 2024). "Loxl1 expression was related to tumor invasion and immune infiltration (B cells, neutrophils, and dendritic cells)." (PMID 38978755, 2024). "Previous studies have revealed that LOXL1 dysregulation was correlated with advanced-stage cancer and worse prognosis, suggesting a link between LOXL1 expression and tumor progression in various cancers." (PMID 38267662, 2024). "Loxl1-related changes in tumor viability/proliferation and invasion were further validated by CCK-8, western blot, wound healing, and Transwell invasion assays." (PMID 38978755, 2024). "First, the data we used were acquired from the public retrospective databases and more in vivo functional experiments should be conducted to validate the effects of LOXL1 on cancer progression and anti-tumor immunity in the future study." (PMID 38267662, 2024). "Loxl1 plays an independent prognostic role in GBM by participating in tumor immune infiltrates and promoting tumor invasion via the EMT pathway." (PMID 38978755, 2024). "PPI network analysis revealed these genes and modules were mainly related to tumor progression (LOXL1, IKBKE, LNX1, FOXA2, FGF17, and FGF2) and immune response (STAT4, IL23R, LTA, ITK, and IL19)." (PMID 36611170, 2023). "And as expected, STEAP3 and LOXL1 were significantly increased in the tumor core compared to the normal brain area." (PMID 37891828, 2023). "Significant increase in the expression of COL5A1 and LOXL1 in tumor tissues was validated by quantitative real‐time polymerase chain reaction (p < 0.05)." (PMID 35152572, 2022). "LOXL1 in colorectal cancer cells can repress tumor growth, invasion, and metastasis by increasing phosphorylation of the kinase MST1/2 to attenuate the transcriptional activity of YAP." (PMID 36293126, 2022). "COL5A1 and LOXL1 expression levels were significantly higher in 18 paired tumor tissues than in cancer‐adjacent tissues (p < 0.05), consistent with the results obtained by RNA‐seq." (PMID 35152572, 2022). "Although the expression of Loxl1 was recently linked to invasive lobular breast cancer (ILC) progression in xenograft models, the effects appeared mainly due to Loxl1-induced tumor growth." (PMID 35292774, 2022). "Intraductal xenografts of invasive lobular carcinoma (ILC) cells faithfully model this breast cancer subtype, and reveal tumor cell intrinsic ECM remodeling as a critical feature of disease progression that can be exploited therapeutically by targeting LOXL1." (PMID 33616307, 2021). "LOXL1 acts as a critical tumor suppressor in regulating tumor growth, invasion, and metastasis by inhibiting the activity of yes-associated protein (YAP)." (PMID 34502094, 2021). "The effects of LOXL1 down‐modulation point to an important role of the enzyme in tumor invasion and progression, making this enzyme a very attractive drug target." (PMID 33616307, 2021).
tumor (continued). "Among the pan‐cancer patients, the overall survival rate in patients with LOXL1‐mutant tumours (n = 15) was relatively lower than that in patients with non‐mutant tumours (n = 5780) (P =.1438)." (PMID 34105806, 2021). "Next, we compared the overall survival rates between patients with LOXL1‐non‐mutant and LOXL1‐mutant tumours from TCGA." (PMID 34105806, 2021). "HCT8-LOXL1, SW480-LOXL1 and their corresponding control cells were slowly injected into the spleen; the overexpression of LOXL1 drastically decreased the number and size of metastatic tumours in the livers of mice." (PMID 32912229, 2020). "The ectopic expression of LOXL1 was found to significantly decrease the size of the xenograft tumours in mice injected with HCT8 and SW480 cells, and corresponding results were observed upon haematoxylin-eosin (H-E) staining." (PMID 32912229, 2020). "In silico analysis showed that LOXL1 was overexpressed in tumor tissues of GC patients with PD and in highly disseminated peritoneal GC cells, relative to that in the control GC patients and cells, respectively." (PMID 33095806, 2020). "Taken together, these observations suggest that LOXL1 acts as a tumour suppressor and facilitates the migration, invasion, and tumourigenesis of CRC cells." (PMID 32912229, 2020). "The results showed that LOXL1 and LOXL4, particularly LOXL1, were expressed at higher levels in tumor tissues." (PMID 32424143, 2020). "Loxl1 codes for an enzyme that oxidizes extracellular matrix proteins, remodels the tumor microenvironment, and is involved in EMT and metastasis." (PMID 32831131, 2020). "We observed a significantly lower expression of LOXL1 in CRC samples than in adjacent non-tumour samples, and the difference in IHC staining scores was statistically significant (P < 0.001)." (PMID 32912229, 2020). "The results were observed after 8 weeks and revealed that compared to the control vector-containing HCT8 cells, LOXL1-overexpressing HCT8 cells had repressed tumour metastasis in the lungs of mice." (PMID 32912229, 2020). "LOXL1 expression was higher in tumor tissues than in normal gastric tissues, and high expression of LOXL1 was a poor prognostic factor in the TCGA dataset." (PMID 33095806, 2020). "Collectively, the in vivo results demonstrated the criticality of the role of LOXL1 as a tumour suppressor in the metastasis of CRC cells." (PMID 32912229, 2020). "As a consequence of collagen reorganization in NSCLC tumor stroma, we showed that LOXL1 supported tumor growth and progression." (PMID 31121900, 2019). "We subcutaneously injected the HCC4006 NSCLC cell line in Loxl1 knockout (Loxl1−/−), heterozygous (Loxl1+/−), and wild-type (Loxl1+/+) mice and measured tumor growth rate." (PMID 31121900, 2019). "Since collagen matrix remodeling and alignment have been shown to mediate metastasis, we investigated the role of LOXL1 in tumor cell invasion." (PMID 31121900, 2019). "Specifically, LOXL1 is able to enhance tumorigenesis and metastasis through active remodeling of tumor-microenvironment." (PMID 28851363, 2017). "Additionally, LOXL1 secreted by tumor cells interacts with other cell types in the tumor microenvironment (TME), accelerating tumor progression." (PMID 40786111, 2025). "Furthermore, recent research has shown that LOXs, including LOX and LOXL1–4, are crucial for tumour metastasis." (PMID 40786111, 2025). "Notably, OSMR, IGFBP2, and LOXL1 are highly expressed in multiple signaling pathways involved in tumor‐related biological processes such as apoptosis, inflammatory responses, EMT, and adherens junctions." (PMID 41498024, 2025). "In addition, LOXs, including LOXL1, contribute to tumour metastasis by generating hydrogen peroxide (H2O2), activating Src/FAK signalling and epithelial–mesenchymal transition (EMT)." (PMID 40786111, 2025). "Additionally, it explores the role of LOXL1 in tumor microenvironment remodeling, tumorigenesis, metastasis, and the molecular mechanisms that underpin these processes." (PMID 40786111, 2025).
tumor (continued). "Additionally, LOXL1 expression was found increased with tumor progression from early stage to advanced stage." (PMID 38267662, 2024). "However, the elaborate mechanisms of how LOXL1 mediates tumor metastasis and progression in CRC are still enigmatic and need to be studied in-depth." (PMID 38267662, 2024). "Functional study found that LOXL1 enhanced tumor cell proliferation, migration and invasion." (PMID 38267662, 2024). "Besides, myeloid-derived suppressor cells (MDSC) were also enriched in LOXL1 high expression group compared to LOXL1 low group, which usually expand during tumorigenesis and exert immunoinhibitory activity by suppressing anti-tumor CD8 + T cells." (PMID 38267662, 2024). "In particular, we confirmed that high Loxl1 promoted tumor invasion with prognostic value." (PMID 38978755, 2024). "The other risk factors LOXL1, LOXL2, and STEAP3 were highly expressed in almost all tumor zones (CT, HBVs, MVP, PAN, PNZ, IT) and showed the lowest expression in the peritumor zone (LE), while the protective factor F5 showed no obvious change between the tumor and peritumor zone." (PMID 37891828, 2023). "However, the tumor-promoting effects of LOXL1 have also been reported successively in various types of cancer." (PMID 36293126, 2022). "In a xenograft model of NSCLC, integrin α11 is reported to regulate the expression of CAF-derived lysyl oxidase like-1 (LOXL1), a matrix cross-linking enzyme, hence supporting tumor growth and immunoresistance through collagen matrix remodeling and collagen fiber alignment both in vitro and in vivo." (PMID 35488263, 2022). "Thus, while the biological effects are different between the two ILC models, in both cases LOXL1 is essential for in vivo tumor progression suggesting that the enzyme is a promising therapeutic target in ILC." (PMID 33616307, 2021). "To test whether LOXL1 function is required for tumor growth and progression and may, hence, be exploited as a therapeutic target, we made use of the natural compound β‐aminopropionitrile (BAPN)." (PMID 33616307, 2021). "IHC showed that LOXL1 was highly expressed in tumor cells from 4 out of 5 GC tissues." (PMID 33095806, 2020). "Furthermore, tumour growth was also inhibited by the overexpression of LOXL1, as observed from the tumour growth curve." (PMID 32912229, 2020). "LOXL1 may function as an important tumour suppressor in regulating tumour growth, invasion and metastasis via negative regulation of YAP activity." (PMID 32912229, 2020). "Furthermore, the suppression of tumour metastasis was more pronounced after the cytoplasmic retention of LOXL1 ∆SP than that observed with LOXL1 in vitro." (PMID 32912229, 2020). "Our clinical findings were consistent with this report, suggesting that LOXL1 may affect tumor progression in GC cells." (PMID 33095806, 2020). "Furthermore, LOXL1 knockdown decreased tumor cell invasion (p < 0.001), confirming the role of LOXL1 in NSCLC cell invasion." (PMID 31121900, 2019). "Loxl1 deletion in mice significantly decreased tumor growth compared to wild-type SCID mice." (PMID 31121900, 2019). "Reintroduction of LOXL1 expression in these cells promotes tumor suppressor activity, suggesting that the role of LOXL1 in tumor progression could depend on the tumor and the cell type in which it is expressed." (PMID 31121900, 2019). "Here, we demonstrated that Loxl1 deletion in mice inhibited NSCLC tumor growth." (PMID 31121900, 2019). "Since the role of integrin α11 in NSCLC may require the contribution of LOXL1, we analyzed the effect of Loxl1 knockout on tumor growth." (PMID 31121900, 2019). "Moreover, LOXL1 can affect the tumour prognosis by affecting immune cell infiltration." (PMID 40786111, 2025). "Remarkably, cancer-associated fibroblast and endothelial cells, which have been reported to promote tumor progression, exhibited strong positive correlations with LOXL1 expression in the majority of cancers, indicating the immune-regulatory role of LOXL1 in cancers." (PMID 38267662, 2024).